CD4 (CD4 molecule)
Diseases named in the same sentence as CD4 in open-access papers (continued):
Sharing a sentence is not in itself a finding about the gene and the disease.
autoimmune disease (continued). "Transfer of CD4+CD25− conventional T (Tc) cells into T-cell-deficient athymic nude mice has been previously reported as a LIP-induced autoimmune model which develops organ-specific autoimmune diseases and systemic antinuclear antibodies (ANAs)." (PMID 28443628, 2017). "Autoimmune diseases develop as a result of loss of tolerance of self-reactive CD4+ T cells." (PMID 28134752, 2017). "Differential transduction and amplification of zinc signals in CD4+ T cells may help to explain the association of MT expression with autoimmune disease, infection and cancer via regulation of CD4+ T cell signaling." (PMID 27251638, 2016). "The types of CD4+ T cell responses elicited by DCs (e.g., Th1, Th2, Th17, Th21, Th22 and regulatory T cells (Tregs)) are associated with either host immunity or inflammatory diseases, including allergic diseases and autoimmune diseases." (PMID 27088111, 2016). "Finally, VDR binding is enriched near SNPs associated with autoimmune diseases in human CD4+ T cells, suggesting that these cells are also important in the effects of 1,25(OH)2D3 in human autoimmunity." (PMID 28163705, 2016). "In the future, CaFlux assay could be adapted to characterizing T-cell responses in a course of autoimmune diseases including measuring the frequency of pathogenic CD4+ T cells." (PMID 27786275, 2016). "The ability of CD4+ T cells to change their phenotype and to specialize into different functional subsets may enhance the risk of autoimmune diseases." (PMID 26964669, 2016). "An increase of IL-1R1 expression and IL-1 production has been reported in aged rodents, suggesting that CD4+ T cells from the animals are highly responsive to IL-1R1 stimulation and prepared to differentiate into Th17 cells, which is closely linked to autoimmune diseases." (PMID 26673738, 2015). "Evidence for CD4+ T-cell involvement in autoimmune disease pathogenesis and for paracrine calcitriol signaling to CD4+ T lymphocytes is summarized to support the thesis that calcitriol is sunlight’s main protective signal transducer in autoimmune disease risk." (PMID 25852682, 2015). "It is also possible that B10 cells might mediate CD4+T cells, thus suggesting an autoimmune disorder associated with a Th2 response." (PMID 26244559, 2015). "Analysis of expression quantitative trait loci in autoimmune disease states and genetic analysis of inter-individual variability in T helper (Th) activation as a function of ancestry and autoimmune disease susceptibility also implicated CD4+ Th cell activation in autoimmune disease pathogenesis." (PMID 25852682, 2015). "Since autoimmune diseases manifest diverse pathogenic mechanisms, a perturbation in immune regulation by CD4 T lymphocytes may be a common phenotype driving these disorders." (PMID 25171173, 2014). "Our current studies demonstrate that mercury-induced autoimmune disease in LAG-3-deficient mice can be partially prevented by adoptive transfer of WT CD4+ T cells, thereby suggesting that LAG-3+ T cells are essential for maintenance of tolerance toward mercury." (PMID 25122007, 2014). "In this study, we tested the hypothesis that premature CD4+ T cell aging can cause autoimmune disease by examining whether premature CD4+ T cell aging exists and causes LIP in our mouse model." (PMID 24586733, 2014). "Secretion of the proinflammatory cytokine Interleukin-17A (IL-17A) is the hallmark of a unique lineage of CD4 T cells designated Th17 cells, which may play a crucial role in the pathogenesis of rheumatoid arthritis (RA) and many autoimmune diseases." (PMID 24340045, 2013). "CD4+T cells are a key factor for the cause of autoimmune diseases." (PMID 24194771, 2013). "CD4+T cells are a key factor for the cause of autoimmune diseases, such as RA." (PMID 24194771, 2013). "Besides, Th17 cells are a recently described effector CD4+ T cell subset characterized by the production of IL-17, which have been implicated in the pathogenesis of several autoimmune diseases." (PMID 22545078, 2012).
autoimmune disease (continued). "The CD8+ T cell deficiency and increased CD4/CD8 ratio in autoimmune diseases are also present in the healthy blood relatives of patients with these diseases, indicating that the abnormalities are genetically determined and not secondary to the disease process." (PMID 22312480, 2012). "The development of autoimmune diseases is promoted by deficiency in a special set of regulatory T cells that are crucial in the maintenance of autologous tolerance and are characterized by the expression of CD4, CD25 and FoxP3 (CD4+CD25+FoxP3+ Tregs)." (PMID 23226562, 2012). "Classic autoimmune diseases that involve inflammation of distinct tissue, such as type I diabetes, multiple sclerosis and rheumatoid and psoriatic arthritis, are usually associated with specific HLA class II alleles, suggesting that a pathogenic CD4+ T cell response is a major cause of disease." (PMID 38665903, 2023). "Th17 cell differentiation: Th17 cells are recognized as efficient CD4 + T cells that perform a fundamental role in autoimmune diseases and inflammation which may be linked with anti-tumor responses, the depletion of this factor may nurture the favorable tumor environment." (PMID 38074464, 2023). "Knowing the imprinted profiles of naїve CD4+ T cells, which have a pivotal role in the onset and development of autoimmune diseases, it may lead, in healthy and pathogenic conditions, to a new field of study not only in the search for therapeutic targets, but also as a risk or prognostic tool." (PMID 35216459, 2022). "Antibody-suppressor cells, namely CXCR5+PD-1−CD8 T cells, may activate effector functions on self-reactive B cells and CD4 Tfh cells leading to tolerance and inhibition of plasma cell formation thus halting autoantibody production associated with many autoimmune diseases." (PMID 36314014, 2022). "Interestingly, GM-CSF+ CD4 T cells have been associated with inflammation in autoimmune diseases." (PMID 34135895, 2021). "Moreover, the CD4+ to CD8+ T cell ratio is also an important cause of autoimmune disease." (PMID 32461982, 2020). "High expression of FR4 and CD73 are recently-described features shared by anergic CD4+ T cells and Treg where both molecules are thought play functional roles in the maintenance of immune tolerance during pregnancy and in individuals susceptible to autoimmune diseases." (PMID 33329540, 2020). "Lastly, the work done to date begs the question of whether T-cell types other than CD8+ and CD4+ T-cells, such as invariant Natural Killer T-cells or Mucosal Associated Invariant T-cells, can also be re-programmed into autoimmune disease-suppressing cell types using MHC-based nanomedicines." (PMID 33574822, 2020). "Our results provide novel insights on the role of CD28 and associated signaling mediators in IL-22 regulation in human CD4+ T cells and may provide the biological bases for the development of new therapeutic strategies to dampen inflammatory and autoimmune disorders." (PMID 33178223, 2020). "Moreover, a better understanding of the role of autoreactive, pathogenic CD4+ T cells in relapses and progression of autoimmune diseases could have major therapeutic implications." (PMID 32106536, 2020). "However, CD4 lymphocytopenia is associated with autoimmune disease." (PMID 25313340, 2014). "Thus, CMV replication in inflammatory lesions has been speculated to drive the differentiation of CD4+ T cells into pathogenic CD28null T cells, thereby aggravating local chronic inflammation in autoimmune disorders." (PMID 21473750, 2011). "More importantly, human CD4 T cells from healthy controls and MS patients were strongly susceptible to PPARγ-mediated suppression of Th17 differentiation, suggesting that PPARγ is a promising molecular target for specific immunointervention in Th17-mediated autoimmune diseases such as MS." (PMID 21234105, 2010). "However, most autoimmune diseases are associated with CD4+ T cells." (PMID 17064404, 2006).
autoimmune disease (continued). "To further explore how the naïve CD4+ T cell state changes in humans in the presence of inflammation, we assessed naïve CD4+ T cell clusters in human autoimmune disease." (PMID 39866877, 2025). "Removal of CD25+ CD4+ cells induced severe autoimmune disease in mice, whereas reconstitution with this subset prevented disease onset." (PMID 41226379, 2025). "Prior studies have reported the presence of NKG2D+CD4+ cells in patients with cancer, autoimmune disease, or chronic infection." (PMID 41597334, 2025). "Overall, CD4+Notch2+Foxp3lo T cells support Treg cell expansion, thereby promoting recovery from autoimmune diseases." (PMID 40702356, 2025). "Tregs, characterized by CD4, CD25, and the transcription factor Foxp3, play a crucial role in controlling inflammation and reducing autoimmune disease risk." (PMID 41012130, 2025). "In certain autoimmune diseases, such as systemic sclerosis and IgG4-related disease, an expansion of CD4+ CTLs was reported." (PMID 40393992, 2025). "Under the combined induction of TGF-β and IL-6, naive CD4+ T cells differentiate into Th17 cells secreting IL-6 and IL-17, participating in inflammatory responses and autoimmune diseases." (PMID 40557038, 2025). "The combination of αCD4 antibodies and autoantigen-induced Treg therapy shows promise for treating autoimmune diseases by temporarily depleting CD4+ T cells and promoting antigen-specific Tregs." (PMID 40918114, 2025). "Regulates CD4+ T cell expansion and differentiation, and is involved in the pathology of autoimmune diseases such as rheumatoid arthritis." (PMID 40230836, 2025). "Autoimmune gastritis (AIG) is a chronic, organ-specific autoimmune disease characterized by progressive destruction of gastric parietal cells driven by autoreactive CD4+ T-cells, epithelial stress pathways, and microbial factors." (PMID 41148791, 2025). "Given the pivotal role of CD4+ T cells in autoimmune diseases, we further investigated the rhythmicity of CD4+ T cells." (PMID 39823532, 2025). "Both cases from our cohort were diagnosed early with T-LGLL, in the fourth decade of life; they had personal and family history of autoimmune disease and presented CD4+ T cell defects." (PMID 40309770, 2025). "Chronic inflammation and autoimmune diseases are driven, in part, by the activation of (auto)reactive CD4+ T-cells, highlighting their potential as therapeutic targets for these diseases." (PMID 40277886, 2025). "As a result, CD4+ T-cells are considered critical drivers of autoimmune disease progression, and safely targeting CD4+ T-cell function is an important strategy in the treatment of autoimmune diseases." (PMID 40277886, 2025). "Collectively, our data demonstrate that Piezo1 contributes to the pathogenesis of CD4+ T-cell–mediated autoimmune disease by restraining CD4+ T-cell activation and maintaining effector memory T cells." (PMID 39492686, 2025). "Given the prominent role of CD4+FOXP3+ T regulatory cells in autoimmune disease, it is relevant to discuss the modulatory roles of B lymphocytes in inverse vaccination." (PMID 40710338, 2025). "In certain autoimmune disorders, autoreactive CD4+ T cells frequently exhibit a Th17 or mixed Th1-Th17 phenotype." (PMID 40364944, 2025). "In autoimmune disorders such as rheumatoid arthritis (RA) and multiple sclerosis (MS), CD4 T cells were traditionally considered the primary effectors." (PMID 40918115, 2025). "Accordingly, CD8+GZMK+ and CD4+GZMK+ T cells are enriched at sites of chronic inflammation in the context of autoimmune diseases and tumors likely contributing to chronicity, tumor immune escape, outgrowth and metastasis." (PMID 41030456, 2025). "Reprogramming autoreactive CD4+ effector T (Teff) cells into immunosuppressive Tregs represents a promising strategy for treating established autoimmune diseases." (PMID 40762956, 2025).
autoimmune disease (continued). "The significance of Tregs is exemplified by the spontaneous onset of autoimmune diseases observed in normal rodents upon depletion of CD25+CD4+ T cells." (PMID 40136531, 2025). "Evidence suggests that T cells are most sensitive to senescence, and senescent CD4+T cells play a crucial role in accelerating autoimmune diseases and other immune-related pathologies." (PMID 40825269, 2025). "CD4+ T cells (T helper and T reg) play an important role in the immune system and are influential in autoimmune diseases (e.g., rheumatoid arthritis, inflammatory bowel disease) and cancer (antitumor immunity)." (PMID 40775564, 2025). "In this Review, we discuss the abnormal RNA modification changes in patients with autoimmune diseases and highlight the effects of these abnormal changes on CD4+ T cells." (PMID 40196109, 2025). "Accumulating evidence suggests that CD4+ naïve T cells, CD4+ Tcm cells, and CD4+ Tem cells have a critical function in the development of autoimmune diseases, such as UC." (PMID 41465029, 2025). "The interaction of CD4+ T cells and B cells is the basis to initiate antibody responses during the clearance of pathogens and the development of autoimmune diseases." (PMID 41177827, 2025). "In experimental studies, IL-10-producing Bregs can convert resting CD4+ T cells to Treg cells and suppress autoimmune diseases." (PMID 40710338, 2025). "The secretion of interferon-gamma (IFN-γ), a pivotal regulator in mediating immune responses against intracellular pathogens and a contributing factor in autoimmune disease mechanisms, is induced by the progression of CD4+ T cells towards TH1 differentiation." (PMID 40230836, 2025). "The IL−17-expressing CD4+ helper T cell (Th) subset is significantly involved in immune response signaling pathways, correlating not only with autoimmune diseases but also with cancer progression." (PMID 40463715, 2025). "In autoimmune diseases like muscle-specific tyrosine kinase antibody-positive myasthenia gravis (MuSK-MG), tacrolimus has demonstrated the ability to suppress CD4 and CD8 T-cell proliferation and significantly reduce Th1 and Th17 responses." (PMID 40757951, 2025). "In this study, we explored the effect of NAM on CD4+ T-cell function to further understand its therapeutic potential in the context of autoimmune diseases." (PMID 40277886, 2025). "In SLE, which is also an autoimmune disease, impaired humoral regulation and hyperactivation of CD4+ T cells are prominent features." (PMID 40718410, 2025). "Circulating Tfh CD4 T cells have been reported in the peripheral blood of healthy humans, and these cells are increased in patients with autoimmune diseases." (PMID 39568245, 2025). "Th17 and Treg cells are both CD4+ effector T cells, which play a critical role in the pathogenesis of inflammatory and autoimmune diseases." (PMID 40079012, 2025). "The CD4+ T cell type was specifically chosen due to its pivotal role in immune regulation and frequent involvement in autoimmune diseases, positioning it as a valuable model for investigating methylation dynamics in disease contexts." (PMID 39888214, 2025). "According to research reports, the infiltration of CD4+ T cells at sites of inflammation is a defining characteristic of autoimmune diseases." (PMID 40332204, 2025). "CD4 T cell dysfunction is often observed in autoimmune diseases, and these cells also play an important role in the autoimmune pathogenesis of vitiligo." (PMID 40078960, 2025). "These two interleukins regulate CD4 + T cell differentiation into Th1 and Th17 cells, mediate the chemotaxis and proliferation of immune cells and further participate in various autoimmune disease pathogeneses." (PMID 39621557, 2025). "Autoantigen−specific CD4+ T cells are central to the development of autoimmune diseases, while the expansion of regulatory T (Treg) cells expressing Forkhead box protein 3 (Foxp3) is essential for mitigating these conditions." (PMID 40702356, 2025).
autoimmune disease (continued). "Itolizumab’s mechanism of action selectively inhibits T-cell proliferation and cytokine production, and it especially affects IL-17 in producing CD4+ T cells (Th17), known to be involved in many autoimmune disorders like psoriasis." (PMID 39996744, 2025). "Memory CD4 T cells were particularly important in the context of autoimmune diseases due to their long-lived nature, effective response to antigens, and unique capacity to mediate recurrent autoimmune responses." (PMID 40475761, 2025). "Recent studies have also explored the role of Themis in CD4+ T cells from other aspects and experimental systems, such as autoimmune diseases." (PMID 40777021, 2025). "Granzyme B (GzmB)-producing CD4+ T cells have been recently reported to participate in the pathogenesis of autoimmune diseases." (PMID 38841892, 2024). "Collectively, our data support MTX-101 as a novel and selective approach to restoring CD8 Treg network functions in the setting of CD4 T cell-driven autoimmune disease." (PMID 39559361, 2024). "Next, we determined the frequency of 4 Tph subsets (Tph1, Tph2, Tph17, and Tph1-17 cells) within CD45RA- memory CD4+ T cells in the blood of patients with various autoimmune diseases including SLE and healthy controls (HC)." (PMID 38448723, 2024). "Prior research focused on the metabolic pathways required for Th1, Th17, and Tregs, as these CD4+ T cell subsets are critical in pathogenesis of cancers and autoimmune diseases." (PMID 39404231, 2024). "As a new subpopulation of CD4+ T cells, Th17 cells play a crucial role in autoimmune diseases and chronic inflammatory responses." (PMID 38347480, 2024). "This enhanced elimination of autoreactive CD4 T cells results in reduced antigen-induced CD4 T-cell activation and epithelial cell death in tissues affected by autoimmune diseases and in a persistently inflammatory mouse model." (PMID 39559361, 2024). "In an animal model of autoimmune disease, CD4+ immune cells, attracted and activated by IL-16, are associated with neuroinflammation." (PMID 38750122, 2024). "The emerging roles of cytotoxic CD4 T cells have been demonstrated in a variety of infection models, autoimmune diseases and cancer." (PMID 38271477, 2024). "While these studies focus on antigen-specific cells, we show here that CD4+ TIA cells that are activated in a TCR-independent manner contribute to this pool of pathogenic cells and accelerate onset of autoimmune disorders, as we have seen for EAE." (PMID 38838013, 2024). "Autoreactive CD4+ T helper cells are critical players that orchestrate the immune response both in multiple sclerosis (MS) and in other neuroinflammatory autoimmune diseases." (PMID 39013878, 2024). "In several diseases we have included here, pathology is mediated far more by some CD4+ T cell subtypes than others, especially for autoimmune diseases." (PMID 38590520, 2024). "IL-23 is the cytokine essential for inducing differentiation of CD4 + T cells into T helper cells that secrete IL-17 (Th17), a key proinflammatory cytokine involved in the pathogenesis of T-cell mediated autoimmune diseases." (PMID 39103899, 2024). "Some autoimmune diseases are believed to arise from the activation of conventional CD4+ T cells that recognize self-antigens." (PMID 39589811, 2024). "Among 180 traits, autoimmune diseases showed significantly high enrichment in NMF features (p = 8.51 × 10−12), suggesting autoimmunity is closely associated with CD4+ T cells." (PMID 38359792, 2024). "Breg play an important role in immune homeostasis and in the regulation of autoimmunity and autoimmune diseases and regulate the generation of peripheral CD4+ Treg cells." (PMID 39051325, 2024). "Abatacept is known to block APC-CD4 T cell interactions resulting in reduced CD4 helper cells across multiple autoimmune diseases." (PMID 38650930, 2024). "Taken together, we comprehensively profiled heritability enrichment on CD4+ T cell gene features across autoimmune diseases." (PMID 38359792, 2024).